CXCL9 (C-X-C motif chemokine ligand 9)
Diseases named in the same sentence as CXCL9 in open-access papers (continued):
Sharing a sentence is not in itself a finding about the gene and the disease.
tumor (continued). "Compared to diluent-treated controls, the treatment group receiving CCL19 had a significant increase in type 1 cytokines (GM-CSF, IFN-γ) and antiangiogenic chemokines (CXCL9, CXCL10) and a decrease in the immunosuppressive cytokine TGF-β at the tumour sites." (PMID 16598185, 2006). "This was coupled with an increase in GM-CSF (two-fold, P<0.01), IFN-γ (4.2-fold, P<0.01), CXCL9 (1.4-fold, P<0.01), and CXCL10 (1.7-fold, P<0.05) within the tumour microenvironment." (PMID 16598185, 2006). "The tumour sites of CCL19-treated mice revealed significant increases in IFN-γ, CXCL10/CXCL10/IP-10, CXCL9/CXCL9/MIG, and GM-CSF." (PMID 16598185, 2006). "Conversely, the lack of cytotoxic T-cell infiltration may be attributable to the epigenetic silencing of T helper 1 (TH1)-type chemokines like CXCL9 and CXCL10, which is known to create a ’cold’ tumor immune contexture (Nagarsheth, Wicha & Zou, 2017)." (PMID 41556056, 2026). "In contrast, M1-like macrophages could produce CXCL9 and CXCL10, activating effector CD8+ T cells, thereby enhancing anti-tumor immunity." (PMID 41635851, 2026). "Among these, the CXCL9+SPP1- subpopulation exhibited macrophages with anti-tumor features, whereas the CXCL9-SPP1+ subpopulation showed macrophages with pro-tumor features." (PMID 42079623, 2026). "Innate immune cells, such as mature dendritic cells (mDCs) and M1-like tumor-associated macrophages (TAMs), secrete cytokines, such as IFN-α, IL-12, IL-18, and TNF, along with chemokines like CXCL9, CXCL10, and CCL21, which effectively suppress tumor angiogenesis." (PMID 40322886, 2025). "Importantly, in Uba1-overexpressing tumors, we detected diminished surface expression of tumor-specific MHC-I and reduction of mRNA levels of Cxcl10, Cxcl9, and MHC-I genes compared with the control." (PMID 39540840, 2025). "Similarly, Cxcl9 and Cxcl10 mRNA expression in murine RAW264.7 macrophages was also increased after coculture with IFN-β–treated Usp5-KO B16 tumor cells." (PMID 41321309, 2025). "Furthermore, DC-derived chemokines, including CXCL9 and CXCL10, guide Teff cell trafficking to tumor sites through CXCR3 receptor binding, facilitating tumor infiltration." (PMID 41281945, 2025). "Given the distinct functional roles of CXCL9+ and SPP1+ TAMs in shaping the tumor microenvironment, CS polarity could serve as a potential biomarker for stratifying patients in immunotherapy." (PMID 40230843, 2025). "Furthermore, the polarization of CS macrophages (defined by CXCL9 and SPP1 expression) unveils a highly coordinated network encompassing variables that promote or suppress tumor progression." (PMID 40936719, 2025). "Similarly, compared to CAF‐S4, CAF‐S5 also upregulates CCL4, CXCL9, CXCL10, CXCL11 and IL1RN suggesting that cytokine and chemokine transcripts are enriched in tumours with high CAF‐S1 and CAF‐S5 and low in the myCAF‐like subset CAF‐S4." (PMID 39743376, 2025). "Additionally, aCD40 enhanced tumoral production of CXCL9 and CXCL10, potent T cell chemoattractants that likely facilitated T cell trafficking from the periphery to the tumor microenvironment." (PMID 40585246, 2025). "When looking at the overall expression pattern of Cxcl9 in tumours, irrespective of the cDC1s, we also observed an enrichment of Cxcl9 transcripts in the parenchymal Region 6‐infTumour, where Cxcl9 expression sometimes overlapped with blood vessels." (PMID 40745918, 2025). "CXCL-9 and CXCL-10 are also known to be endogenous tumor angiogenesis inhibitors." (PMID 39996769, 2025). "Additionally, ENKTL tumor cells can express DPP4, which cleaves CXCL2, CXCL9, and CXCL10, chemokines that recruit T cells and NK cells into the tumor microenvironment, depleting the number of anti-tumor effector cells." (PMID 41295262, 2025).
tumor (continued). "In the Oncology VascHT29 Combo ELECT system, Keytruda (50,000 ng/mL) also reversed the hsa/mtCXCL8-mediated inhibition of key adhesion molecules like VCAM-1, CXCL-10, CXCL-9, and CD69 at the highest dose, promoting immune cell adhesion and recruitment into the tumor site." (PMID 40124384, 2025). "The type-1 interferon response leads to autocrine activation of IFNAR (interferon α/β receptors), resulting in CXCL9 (C-X-C motif chemokine ligand 9) and CXCL10 (C-X-C motif chemokine ligand 10) production, which subsequently stimulates T lymphocyte infiltration into the tumor." (PMID 40557162, 2025). "Furthermore, CXCL9+ TAMs were predominantly enriched in the tumor margin, while SPP1+ TAMs displayed consistently increased expression from normal to tumor core regions, suggesting their potential involvement in malignant progression." (PMID 40725473, 2025). "Eosinophils can recruit tumor-specific CD8+ T cells into the tumor microenvironment by secreting chemokines such as CCL5, CXCL9, and CXCL10, and induce macrophage polarization toward the M1 phenotype, thereby enhancing the immune system’s ability to recognize and destroy tumor cells." (PMID 39949762, 2025). "Furthermore, the SNHG26‐CDKN2A axis modulated the tumour immune microenvironment by regulating CD8+ T cell cytotoxicity and chemokine expression, specifically downregulating CXCL9 and CXCL10, which are critical for T cell recruitment." (PMID 41310877, 2025). "Mechanistically, ROS1-mutant tumors displayed an immunosuppressive tumor microenvironment characterized by diminished CD8+ T cell infiltration, attenuated interferon-γ signaling, and downregulation of immune-related genes (CXCL9, CXCL10, IFNG, PD-L1)." (PMID 40873541, 2025). "In addition, the pulmonary microbiota can upregulate CXCL9 in both cancer and myeloid cells, facilitating recruitment of CD8+ T cells into the tumor core and thereby improving the therapeutic efficacy of nivolumab." (PMID 41516132, 2025). "In addition, cGAS-STING activation also promotes the secretion of chemokines (e.g., C-X-C motif chemokine 9 (CXCL9), CXCL10 and C-C motif chemokine ligand 5 (CCL5)), and enables CTL infiltration and tumor recognition." (PMID 40849659, 2025). "Interferon cascade activation induces the production of chemokines, such as CXCL9, which promotes the recruitment of CD8+ T cells to the tumor microenvironment and stimulates the expression of CXCL13, intensifying immune infiltration and improving the response to checkpoint inhibitor treatments." (PMID 40647506, 2025). "In tumor models, Tim3 on BATF3+CD103+ cDC1s suppresses the production of CXCL9, a chemokine critical for the recruitment of effector CD8+ T cells to the tumor microenvironment, and blockade of Tim3 enhances CXCL9 production and improves antitumor immunity." (PMID 41177809, 2025). "PD-1 inhibition restructures the tumor microenvironment: re-energized CTLs secrete IFN-γ that polarizes macrophages towards an M1 phenotype and stimulates stromal cells to secrete the chemokines CXCL9/10, which additionally attract NK cells to the tumor." (PMID 40723882, 2025). "Tumor grade was similar between Cxcl9/10- and tdTomato-overexpressing groups, suggesting that these chemokines do not affect tumor invasiveness." (PMID 41332581, 2025). "Interestingly, chemokines such as CXCL9, CXCL10 and CXCL13 are involved in fostering the hot tumour milieu." (PMID 40852716, 2025). "For example, CXCL9/CXCR3, which is known to recruit cytotoxic T cells, may counteract the tumor‐promoting effects of CXCL12/CXCR4 by enhancing anti‐tumor immunity." (PMID 40145607, 2025). "In addition, the oHSV treatment resulted in higher expressions of Ccl4, Cxcl9, Ccl21 and Cxcl10 in the MC38 tumours." (PMID 39219056, 2025). "CXCL9 and CXCL10 can be secreted by tumor cells and immune cells." (PMID 41332581, 2025).
tumor (continued). "Furthermore, CXCL9/10-expressing cDC1 and IFN-γ-stimulated tumor cells can also recruit CXCR3+ TRM or TE cells into tumors through T cell tumor infiltration." (PMID 41194931, 2025). "Furthermore, CXCL9 and SPP1 expression in macrophage polarization has been shown to orchestrate a spatially structured and tightly regulated network of tumor-promoting and tumor-inhibiting factors, involving diverse populations of tumor-associated cells." (PMID 40940867, 2025). "However, recent studies revealed that the autocrine CXCL9, −10, −11/CXCR3 axis in tumor cells facilitates proliferation, angiogenesis, and metastasis as well as reduced CXCR3 expression on CD8+ T cells." (PMID 40447617, 2025). "Moreover, we used an ELISA kit to detect the secretion of CXCL9 and CXCL10 in the subcutaneous and orthotopic tumor models." (PMID 40008893, 2025). "The ligands CXCL9, CXCL10, and CXCL11 all bind to CXCR3 and are primarily secreted by immune cells such as leukocytes and macrophages, as well as by dendritic cells, fibroblasts, and tumor cells." (PMID 40362215, 2025). "Tumor rejection is accompanied by antigen spreading, abscopal effects, and infiltration by clonally diverse T cells, dendritic cells, and MHC I/II+ macrophages producing CXCL9/10, CCL5/8, and TNF." (PMID 41256707, 2025). "Single-cell RNA sequencing of tumor samples from patients with HCC (GSE189903) revealed that intratumoral PD-L1(+) TAMs were enriched for immune-related signaling pathways and expressed chemokines including CXCL9, CXCL10, and CXCL11." (PMID 41027276, 2025). "Notably, in the context of squamous cell carcinoma of the tongue, CXCL9 has been demonstrated to interact directly with tumor cells via its receptor CXCR3, thereby promoting tumor invasion and metastasis." (PMID 40909948, 2025). "Conversely, DNMT1-mediated methylation silences chemokines such as CXCL9 and CXCL10, leading to reduced anti-tumor immune cell infiltration; the restoration of TET1 and TET2 can reverse this effect and improve the efficacy of immune checkpoint inhibitors (ICIs)." (PMID 41394878, 2025). "Our analysis indicated that the abundance of immunosuppressive CD8 T cells and Treg cells, particularly in advanced tumours, along with reduced IFN‐Mac_CXCL9 activity, may contribute to therapeutic resistance." (PMID 41275425, 2025). "Key chemokines involved in CD8+ T cell recruitment (CCR3, CXCL10, CXCL9) and their receptors (CCR2, CCR5, CXCR3) were consistently downregulated in FAM174B-high tumors, potentially limiting effector immune cell trafficking to the tumor microenvironment." (PMID 40959568, 2025). "Therefore, we chose to inhibit the CXCL9 pathway via its receptor CXCR3, as this cytokine has been described as influencing tumor cell growth." (PMID 40362215, 2025). "CXCL9/10 attract CD8+ and CD4+ T cells and facilitate their recruitment to tumor sites." (PMID 41332581, 2025). "Indeed, looking at the most variable genes in the immune compartment of the TME before and after ACT, a core IFNγ response gene set (for example, Cxcl9, Gbp2 and Slamf7) was strongly increased in NTT tumours." (PMID 39604727, 2025). "M1 macrophages promote tumor destruction by directly killing tumor cells and by enhancing the recruitment and activation of cytotoxic CD8+ T cells and natural killer (NK) cells via secretion of CXCL9, CXCL10, and CXCL11 chemokines." (PMID 40475782, 2025). "CAFs promote tumour progression by secreting ECM components, enzymes, cytokines, chemokines, and growth factors while modulating T-cell responses and angiogenesis via TGF-β, IL-6, CXCL9, and VEGF." (PMID 40361472, 2025). "HMGB1, on the other hand, activates the NF-κB pathway in Mφ via TLR4/RAGE signaling, promoting the secretion of chemokines such as CXCL9/CXCL10 and recruitment of effector T cells into the tumor microenvironment, while inhibiting Mφ polarization towards the M2 phenotype." (PMID 41019083, 2025).
tumor (continued). "Notably, however, our data also illustrates a strong induction of TH1‐type chemokines CXCL9, CXCL10 and CXCL11, which are ligands for CXCR3 and critical to drive T‐cell recruitment to the tumour sites." (PMID 39743376, 2025). "The Cxcl9/10 positive cells are enriched in the HER2+ tumor compartment, but not the surrounding CD45+ immune compartment." (PMID 41332581, 2025). "Simultaneously, chemokines such as CXCL9, CXCL10, and CCL5 regulate T-cell recruitment, whereas LFA-1 and adhesion molecules like ICAM-1 govern their infiltration and retention within the tumour." (PMID 40361472, 2025). "Moreover, pulmonary microbiota-mediated upregulation of CXCL9 in cancer and myeloid cells recruits CD8+ T cells into the tumor core and enhances the efficacy of nivolumab." (PMID 41516132, 2025). "Thus, we confirmed the increase in the number of CXCL9+ cells and CXCL13+ cells and their concentration within and peripheral to the tumour in all four patients following post-PD-L1-CRT." (PMID 40670667, 2025). "In turn, these macrophages, together with DCs, may increase the recruitment of tumor-specific and stem-like TCF+ T cells through antigen presentation by MHC and CXCL9 production." (PMID 40027748, 2025). "The CXCL9:SPP1 (CS) expression ratio, or CS polarity, has been identified as a key determinant of whether TAMs adopt an anti-tumor or pro-tumor phenotype." (PMID 40230843, 2025). "Therefore, the combination therapy with TTFields and anti-PD-1 activates STAT1 and IRF1 through ICD in tumor tissue, enhancing the CCL2/8-CCR2 axis and CXCL9/10-CXCR3 axis, which recruits CD8+ T and CD4+ T cells to infiltrate and kill tumor cells." (PMID 40098106, 2025). "And macrophage-derived CXCL9 and CXCL10 are important for ICB-induced anti-tumor immunity." (PMID 38758367, 2024). "Activation of the cGAS/STING pathway and production of immunomodulatory molecules such as INF-α, IL-6, CXCL9 and CXCL10 were described to be involved in the enhanced migration of immune cells in cancer, particularly macrophages, and regulate anti-tumor immune response." (PMID 38587186, 2024). "Moreover, in miR-29 overexpressing tumors, there were significant changes in cytokine and chemokine expression, such as upregulation of CCL5, CCL11, CXCL9, CXCL11, and CXCL16, known for their anti-tumor effects." (PMID 38890285, 2024). "Furthermore, we showed that VC increases chemokine gene CXCL9/-10/-11 expression in a TET2-dependent manner, leading to type I T cell attraction to tumor sites and to enhanced checkpoint inhibitor responses." (PMID 39388288, 2024). "CXCL9-Fc and CXCL10-Fc significantly reduced tumor growth (day 13 P<0.05)." (PMID 39474427, 2024). "This shift from CCL5/CXCL9/CXCL10 to CXCL8/CXCL12/CCL22 production was attributed to NFκB-mediated induction of COX2/PGE2/EP4, along with upregulation of IDO1 and IL-10, further contributing to the immunosuppressive tumor microenvironment." (PMID 39409924, 2024). "Recent research suggested that tumor macrophage polarity, characterized by CXCL9 and SPP1 expression rather than traditional M1 and M2 markers, exhibits a significantly strong prognostic correlation in HNSCC." (PMID 38962427, 2024). "In summary, these findings demonstrate that in preclinical PDAC models silencing of Gsdmc unleashes CXCL9 as a key downstream mechanism for the TME‐modulating effects of GSDMC, resulting in an uprise of tumor‐infiltrating immune cells and a subsequent reversal of tumor progression." (PMID 39297408, 2024). "RT combined with CAR-T cells can stimulate the production of chemokines by immune cells (such as macrophages and dendritic cells), endothelial cells, and even the tumor cells themselves, including C-C motif chemokine ligand 2 (CCL2) and C-X-C motif ligand 9 (CXCL9)." (PMID 39578426, 2024). "Immunotherapeutic strategies that augment tumor cell expression of MHC class II, CXCL9, and CXCL10 may improve parenchymal trafficking of immune effector cells in ONB and augment immunotherapeutic responses." (PMID 38822345, 2024).
tumor (continued). "Indeed, the expression of CCL5, IFNG, CXCL9 and CXCL10 positively correlated among themselves as well as with the numbers of tumor-infiltrating NK cells in the original biopsy." (PMID 38167224, 2024). "Certain chemokines (such as CXCL9 and CXCL10) can promote anti-tumor immune responses, while others (like CCL2 and CXCL12) may facilitate tumor progression." (PMID 39030403, 2024). "These three signatures consist of myeloid-focused cytokines (TNFa, GM-CSF, and IL-1b), chemokines (CCL3, CCL4, CCL5, CXCL9, and CXCL10), and an effector T-cell-derived cytokine (IFNg) and represent important aspects of a macrophage-based anti-tumor immune response." (PMID 39199551, 2024). "A recent study in a murine melanoma model demonstrated a failure in the trafficking of CAR-T cells in the tumor due to the absence of T-cell trafficking signals CXCL9 and CXCL10, produced by DCs." (PMID 38785789, 2024). "In vivo DC trafficking studies reveal that IT CXCL9/10-DC vaccines, although short-lived, increased the levels of CXCL9/10 within the TME and induced rapid infiltration of endogenous DCs and T cells into the tumor." (PMID 38518770, 2024). "Furthermore, IFN-γ produced by tumor-infiltrating CAR-T-cells led to the recruitment and activation of iNOS+ tumor macrophages, further upregulating the expression of the CXCR3 ligands CXCL9 and CXCL10." (PMID 38397092, 2024). "Treatment of KPL-3M (TMB high) tumor-bearing mice with i.p. anti-PD-1 or IT CXCL9/10-DC monotherapy provided modest antitumor efficacy, with no observed tumor eradication." (PMID 38518770, 2024). "CXCL9 expression did not correlate with age (p = 0.953), T stage (p = 0.150), N stage (p = 0.096), or tumour-node-metastasis (TNM) stage (p = 0.093)." (PMID 38957805, 2024). "Importantly, blockade of IFNγ through anti-IFNγ antibody (Ab) treatment, abolished the anti-tumor therapeutic effect of SRC-3 KO Tregs, which further solidifies the centrality of the IFNγ/CXCL9 axis to SRC-3 KO Treg-mediated tumor clearance." (PMID 38698860, 2024). "Radiotherapy also induces the expression and release of chemokines such as CXCL9, CXCL10, and CXCL16 in tumor cells, promoting the migration of effector T lymphocytes to tumor sites, modulating the immune status of the TME, and activating the body’s anti-tumor immune response." (PMID 38809459, 2024). "CXCL9 binds to CXCR3 and mediates immune cell infiltration and activation in the tumor environment." (PMID 38245587, 2024). "Local activation of the IFNγ/CXCL9 axis, with no detectable increase in IFNγ within the lymphatic system, results in an immunologically hot (inflamed) tumor, but with minimal impact outside of the TME." (PMID 38698860, 2024). "Thus, although suppressive functions are generally attributed to TAMs, this specific role of CXCL9 and CXCL10 in anti-tumor immunity has suggested a potential use of TAMs to prevent T cell exhaustion and promote anti-PD-L1 responses." (PMID 39596815, 2024). "CXCL9 is secreted by several immune and non-immune cells, including T lymphocytes, eosinophils, macrophages, dendritic cells, fibroblasts, tumor cells, and endothelial cells." (PMID 38349864, 2024). "Mechanistically, the immune effector stromal predilection appears driven by low tumor cell MHC class II (HLA-DR), CXCL9, and CXCL10 expression as those tumors with increased tumor cell expression of each of these mediators correlated with significant increases in T cell infiltration." (PMID 38822345, 2024). "While IL-1α KO tumors contained lower levels of chemokines, such as CCL2 and CXCL1/2/3, known to attract MDSCs into the tumor, they showed higher expression of CCL5, CXCL9/10, which could attract T lymphocytes and NK cells." (PMID 38612760, 2024). "Furthermore, proinflammatory cytokines including CXCL9, TNF-α, CCL4, and CCL3 were also upregulated in the tumor following the combined therapy, further demonstrating the change in the immune environment." (PMID 38705987, 2024).